CFAP43 (cilia and flagella associated protein 43)
Description:
Flagellar protein involved in sperm flagellum axoneme organization and function (By similarity). Involved in the regulation of the beating frequency of motile cilia on the epithelial cells of the respiratory tract (By similarity).
Synonyms: C10orf79; WDR96; FLJ36006; bA373N18.2; FLJ22944; HYDNP1; SPGF19
Tractability: Small molecule: a structure with a bound ligand is known. Antibody: its Gene Ontology location is reachable by antibodies, with medium confidence. PROTAC: ubiquitination databases record sites on it.
Gene: Protein-coding gene on chromosome 10 (104,129,888 to 104,232,364, reverse strand). Ensembl gene ENSG00000197748.
Subcellular location: Cell projection, cilium, flagellum; Cytoplasm, cytoskeleton, flagellum axoneme; Cytoplasm, cytoskeleton, cilium axoneme
Subcellular location (Human Protein Atlas): Flagellar centriole; Nucleoplasm; Cytosol; Mid piece; Nuclear membrane; Principal piece
Gene Ontology:
Biological process: sperm axoneme assembly; regulation of cilium beat frequency; cilium movement; flagellated sperm motility
Cellular component: axoneme; 9+2 motile cilium; motile cilium
Genetic constraint (gnomAD): Loss-of-function variants: 121 observed, 180.33 expected, observed/expected ratio (o/e) 0.67, 90% interval 0.58 to 0.78. The upper end of that interval is the gene's LOEUF score, 0.78, which puts it in group 3 of 6, group 1 being the genes least tolerant of losing a copy. Missense variants: 1,598 observed, 1,819.5 expected, observed/expected ratio (o/e) 0.88, 90% interval 0.84 to 0.92. Synonymous variants: 585 observed, 640.5 expected, observed/expected ratio (o/e) 0.91, 90% interval 0.85 to 0.98.
Gene-disease validity (ClinGen):
ClinGen rates the evidence that CFAP43 causes each of these diseases.
spermatogenic failure 19 (autosomal recessive): Definitive.
primary ciliary dyskinesia (autosomal recessive): Limited. A rare, genetically heterogeneous, primarily respiratory disorder characterized by chronic upper and lower respiratory tract disease.
normal pressure hydrocephalus (autosomal dominant): Disputed.
Homologues: Orthologues: chimpanzee CFAP43 (99% identical), macaque CFAP43 (95% identical), rabbit CFAP43 (81% identical), pig CFAP43 (81% identical), dog CFAP43 (80% identical), guinea pig CFAP43 (76% identical), rat Cfap43 (75% identical), mouse Cfap43 (74% identical), tropical clawed frog cfap43 (46% identical), zebrafish cfap43 (39% identical), Drosophila melanogaster CG17687 (17% identical).
Diseases named in the same sentence as CFAP43 in open-access papers:
CFAP43 is named in the same sentence as 13 diseases in open-access papers, as found by Europe PMC text mining. Sharing a sentence is not in itself a finding about the gene and the disease. The quoted sentences say what the papers report.
male infertility (9 papers, 2018 to 2025). The inability of the male to effect fertilization of an ovum after a specified period of unprotected intercourse. "Motility mutants analysed in our screen also included deletions of genes with human orthologs linked to ciliopathies (such as hydin) or male infertility (CFAP43 and CFAP44)." (PMID 31242261, 2019). "CFAP43 participates in the formation of flagellar axonemes during spermatogenesis as mice mutant for Cfap43 display male infertility consistent with observations in male sterile patients." (PMID 39596622, 2024). "Recent whole-exome sequencing of men with MMAF (multiple morphological abnormalities of the flagella) revealed that biallelic mutations in CFAP43 and CFAP44 result in diverse morphological sperm defects and male infertility." (PMID 29687140, 2018). "It is currently not known whether mutations in CFAP52 affect male fertility although mutations in WD-repeat proteins, as e.g. in WDR66/CFAP251, WDR96/CFAP43, and WDR52/CFAP54, causing human male infertility due to the sperm flagella defects have been reported." (PMID 32859975, 2020). "All individuals with CFAP43 or CFAP44 mutations were unrelated; to our knowledge, none carried rare variants in genes previously reported to be associated with male infertility." (PMID 29449551, 2018).
Hydrocephalus (8 papers, 2021 to 2025). Hydrocephalus is an active distension of the ventricular system of the brain resulting from inadequate passage of CSF from its point of production within the cerebral ventricles to its point of absorption into the systemic circulation. "Mutation of Cfap43 causes a morphologic abnormality of ependymal cilia and consequent hydrocephalus." (PMID 35047005, 2021). "Mutation in CFAP43, encoding a protein associated with ependymal cilia, was also identified as a cause of familial NPH, and CFAP43 knock-out mice exhibited hydrocephalus due to morphologic abnormality of motile cilia." (PMID 33874972, 2021). "It is worth noting that a nonsense variation in the CFAP43 gene has been linked to adult-onset normal-pressure hydrocephalus, suggesting that this gene may also be involved in the functioning of cilia in the ventricles of the brain." (PMID 41341611, 2025). "The Cfap43 protein is important for the normal structure and function of motile cilia and sperm flagella, and homozygous deletion of this gene in mice causes abnormalities in motile cilia structure, infertility, and hydrocephalus in an autosomal recessive manner." (PMID 38100419, 2023). "Subsequently, the authors generated Cfap43-/- mice to confirm the effect of the truncation in CFAP43 on the pathogenesis of hydrocephalus." (PMID 33999288, 2021). "The mutant genes related to motile cilium dysfunction on ependymal cells, and consequent hydrocephalus development may include Ccdc39, Celsr2, Celsr3, Cetn2, Dvl, Foxj1, Hydin, Mdnah5, Pkd1, Tg737, Daple, Dnah14, Cfap43, Cwh43, Eml1, Fmn2, Tmem67, and Zcchc8." (PMID 35047005, 2021). "Several mutations in Ccdc39, Celsr2, Celsr3, Cetn2, Dvls, FoxJ1, Hydin, Mdnah5, Pkd1, Tg737, Daple, Dnah14, Cfap43 and Cwh43 genes, which were related to the structure or function of motile cilia on ependymal cells, have been reported to develop hydrocephalus in animal models." (PMID 33874972, 2021). "Unfortunately, these investigators only studied the effects of CFAP43 mutation in homozygous CFAP43−/− knockout mice; heterozygous CFAP43+/− mice were not examined to determine whether they also developed hydrocephalus." (PMID 38100419, 2023).
asthenozoospermia (4 papers, 2018 to 2025). "Our findings provide the first evidence of a CFAP43 genetic variation causing asthenospermia-related infertility in Palestine." (PMID 41341611, 2025). "Four patients with an extreme (oligo)asthenozoospermia had one homozygous or two heterozygous pathogenic variant(s) in MMAF‐associated genes (CFAP43, CFAP69, DNAI1, and FSIP2)." (PMID 39180390, 2025). "Mutations in CFAP43 lead to severe asthenozoospermia and multiple morphological abnormalities of the sperm flagellum (MMAF) in both humans and mice." (PMID 39596622, 2024). "Interestingly, previous reports have indicated that missense variants in CFAP43 are associated with milder symptoms manifested by mild asthenospermia." (PMID 41341611, 2025).
Infertility (3 papers, 2018 to 2025). "Several studies have reported genetic variations in CFAP43 as a causative factor for MMAF in infertility patients, and this was further confirmed by functional studies and various knockout mouse models." (PMID 41341611, 2025). "Because all KO strains for Cfap43 presented the same reproductive phenotype (identical sperm morphology associated with complete infertility), we randomly chose one and restricted our study to a strain with a 4 bp deletion in exon 21 (delAAGG)." (PMID 29449551, 2018). "The CFAP43 gene, alternatively recognized as WDR96, exhibits widespread expression across gonadal tissues, and early studies have shown that mutations in the CFAP43 gene cause infertility in Trypanosoma and humans." (PMID 38540412, 2024). "Recently, biallelic loss-of-function mutations in the CFAP43 gene (cilia- and flagella-associated protein 43, MIM#: 617592), which encodes a protein necessary for normal sperm flagella axonemal organization, were reported as a causative factor of MMAF in patients with infertility." (PMID 41341611, 2025).
chronic sinusitis (1 paper, 2023). "A recent report on a family with familial iNPH identified a heterozygous mutation in the cilia-associated protein, CFAP43, as a possible cause of chronic sinusitis and familial NPH in two affected family members, suggesting an autosomal dominant effect." (PMID 38100419, 2023).
dilatation (1 paper, 2021). "Cfap43-/- mice showed ventricular dilatation, while Cfap43+/- mice showed no obvious differences from the wild-type mice." (PMID 33999288, 2021).
Respiratory distress (1 paper, 2024). Respiratory distress is objectively observable as the physical or emotional consequences from the experience of dyspnea. "However, no other hallmark features of PCD, such as neonatal respiratory distress and chronic ear infections, were identified in patients with a heterozygous CFAP43 variant." (PMID 39572557, 2024).
CFAP43 also shares sentences with these, for which no sentence is quoted: normal pressure hydrocephalus (2 papers); ciliopathies (1); cone-rod dystrophies (1); dysplasia of fibrous (1); infection (1); primary ciliary dyskinesia (1).